CD68 (CD68 molecule)
Diseases named in the same sentence as CD68 in open-access papers (continued):
Sharing a sentence is not in itself a finding about the gene and the disease.
keloid (4 papers, 2019 to 2023). An irregularly shaped, elevated mark on the skin caused by deposits of excessive amounts of collagen during wound healing. "Notably, monocytes co-cultured with the reconstructed keloid scar as well as reconstructed normal skin skewed towards the M2 macrophage-like phenotype typically involved in tissue remodelling and associated with fibrosis, by becoming CD68+/CD206+." (PMID 31187196, 2019). "Co-culturing with either reconstructed normal skin or keloid skin equivalents generated macrophages that were predominantly CD68+/CD206+, which is characteristic of the more fibrotic M2-type macrophages." (PMID 31187196, 2019). "Moreover, the CD163+/CD68+ ratio was higher in keloids compared with normal skins (P < 0.05), indicating that enriched macrophages in keloids were mostly the M2 type." (PMID 36757802, 2023). "The ratio of immune cells was verified by immunohistochemistry, and the results indicated that there were more CD8+ and CD68+ cells and fewer CD4+ cells in the keloid compared to the surrounding normal skin tissue." (PMID 35990663, 2022). "The results of the image mass spectrometry of an extensive immune panel including 25 markers indicated that CD68, CD14, and CD16 positive macrophages and CD11c-positive DC cells were enriched in keloids, which is consistent with the results of scRNA-seq." (PMID 35990663, 2022). "To summarize, culturing monocytes in vitro induced a CD68+ macrophage-like phenotype, which further differentiated into a CD68+/CD206+M2 macrophage-like cell when co-cultured with either reconstructed normal skin or keloid models." (PMID 31187196, 2019).
leiomyosarcoma (4 papers, 2014 to 2025). An uncommon, aggressive malignant smooth muscle neoplasm, usually occurring in post-menopausal women. "In leiomyosarcomas, increased tumor-associated macrophage (TAM) infiltration, identified using CD163 and CD68 markers, correlates with worse survival outcomes, particularly in non-gynecologic subtypes, suggesting its utility as a prognostic marker." (PMID 40423041, 2025). "Regarding the macrophage polarization, a higher proportion of M2-like macrophages than M1-like macrophages was observed, particularly in UPS (adjusted mean CD163/CD68 = 20.7) and leiomyosarcoma (adjusted mean CD163/CD68 = 17.4)." (PMID 33802565, 2021). "Macrophage infiltration of STS has been previously reported, and CD68 expression has been reported to have prognostic significance in leiomyosarcoma; in addition, some leiomyosarcoma cells were shown to produce M-CSF in vitro." (PMID 30999901, 2019).
leprosy (4 papers, 2011 to 2025). Leprosy is a chronic infectious disease affecting primarily the skin and peripheral nervous system. "IHC tests corroborated that the increase of Runx-1 in leprosy patients is linked to the presence of macrophages marked with CD68 in the inflammatory infiltrate." (PMID 32265900, 2020). "Although macrophages are a key cell in the leprosy granuloma, only one small study has looked at the distribution of macrophages in leprosy reactional skin lesions and high numbers of CD68 cells were found in T1R lesions." (PMID 22180790, 2011). "Furthermore, the CD68 level is positively correlated with the production of iNOS in the microbicidal response in TT form of leprosy, which is one of the main enzymes that induce the production of NO and free radicals." (PMID 30442123, 2018). "The predominance of CD68 in the LL form of leprosy has been previously reported." (PMID 30442123, 2018). "We analyzed the presence of M4 macrophage markers (CD68, MRP8, MMP7, IL-6, and TNF-α) in 33 leprosy skin lesion samples from 18 patients with tuberculoid leprosy and 15 with lepromatous leprosy by immunohistochemistry." (PMID 30442123, 2018). "The double positive labeling for CD68 and MRP8 confirmed the presence of M4 macrophages in leprosy skin lesions." (PMID 30442123, 2018).
leukoplakia (4 papers, 2015 to 2025). A white patch or plaque on a mucous membrane that cannot be characterized clinically or pathologically as any other disease. "We examined the infiltration of macrophages for various pathological grades of leukoplakia using antibodies to CD68, CD80, and CD163." (PMID 26242181, 2015). "In contrast, Oral Leukoplakia samples showed a significantly (p ≤ 0.032) increased cell density and Labeling Index (LI) of IL-23R and CD68 positive cells compared to Controls (mean IL-23R 64 cells/mm2 vs. 5 cells/mm2 and mean CD68 103 cells/mm2 vs. 8 cells/mm2)." (PMID 40297579, 2025). "Comparing Oral Lichen Planus and Oral Leukoplakia, CD163 cell density (mean 514 cells/mm2 vs. 50 cells/mm2, p=0.029) and CD163/CD68 expression ratio (2.26 vs. 0.51, p=0.029) were significantly higher in Lichen lesions." (PMID 40297579, 2025). "Immunohistochemical staining of CD68, CD80, and CD163 on the normal oral mucosa and oral leukoplakia revealed that the three macrophage markers were rarely found in the normal oral mucosa." (PMID 36105288, 2022). "The abundance of CD68 and CD163 in OSCC were significantly higher than those in normal oral mucosa and oral leukoplakia." (PMID 36105288, 2022). "Using CD68 (pan-MΦ), CD80 (M1 MΦ), CD163 (M2 MΦ), and a simple binary model of macrophage phenotype (M1-CD80 versus M2-CD163), they could only observe a significant increase in CD163+ cells in dysplastic leukoplakias, while CD68 and CD80 remained the same." (PMID 37190121, 2023).
liver diseases (4 papers, 2012 to 2024). "In addition to this biomarker, the hepatic microenvironment generally, and CD68+ hepatic macrophages in particular, express multiple genes and proteins associated with macrophage-targeting molecules already under study for the treatment of other liver diseases, as well as cancer." (PMID 39635525, 2024). "CD68+ MFs accumulate in perisinusoidal and periportal regions in the liver of PSC patients irrespective of their IBD status and CD68+ CD206+ MFs are more abundantly present in the livers of PSC patients compared to other liver diseases." (PMID 34831182, 2021).
metastatic carcinoma (4 papers, 2019 to 2023). A carcinoma which has spread from the original site of growth to another anatomic site. "Myeloid features and markers (CD163, CD33, CD68 etc.)can be seen in metastatic cancer cells." (PMID 34257573, 2021). "We assessed the proportion of DAB2+, CD68+ and double labelled (DAB2+ CD68+) cells in matched HGSOC patient tissues from primary and metastatic cancers." (PMID 37815603, 2023). "Our results show that cellular SR-A immunoreactivity is similar to that of CD68 in nonmalignant tissue-resident macrophages, lymph nodes with metastatic carcinoma, nodal THRLBCL and extra-nodal CHL." (PMID 31714922, 2019).
periapical granuloma (4 papers, 2017 to 2022). Chronic nonsuppurative inflammation of periapical tissue resulting from irritation following pulp disease or endodontic treatment. "In the periapical granuloma lesions, five out of eight samples were identified to contain CD68+ cells." (PMID 30631444, 2018). "CD68+ cells identified in the five periapical granuloma lesions were abundant but were mainly located in localized areas of the granulation tissue." (PMID 30631444, 2018). "Immunohistochemical stainings showed that CD4+ helper and CD8+ cytotoxic T lymphocytes, along with CD20+ B lymphocytes and CD68+ macrophages, were diffusely distributed in all periapical cysts and in some periapical granulomas, but CD79α+ plasma cells characterized especially periapical granulomas." (PMID 34441046, 2021). "The protocol for immunohistochemical procedures of TLR2, CD38, CD68 and CD83 have been standardized and the expression of each cell marker (TLR2, CD38, CD68 and CD83) within refractory periapical granuloma was identified." (PMID 30631444, 2018). "Refractory periapical granuloma consistently expressed TLR2 through lymphocytes and plasma cells (CD38+), macrophages and monocytes (CD68+) and mature dendritic cells (CD83+)." (PMID 30631444, 2018). "The co-expression of CD68 and TLR2 on cells was identified in five periapical granuloma samples." (PMID 30631444, 2018).
prostate adenocarcinoma (4 papers, 2009 to 2022). "However, our previous study in murine TRAMP-C1 prostate adenocarcinoma demonstrated that the CD68+ TAMs have no preference for PIMO+ hypoxia region in the control, untreated tumors." (PMID 22888475, 2012). "An excisional biopsy revealed a non-caseous epithelioid granuloma consisting of CD-68 positive histiocytic cells with infiltration of T-lymphocytes and eosinophils; skin metastasis from prostatic adenocarcinoma was ruled out through histological and immunohistochemical analysis." (PMID 19918419, 2009).
pulmonary tuberculosis (4 papers, 2011 to 2025). A bacterial infection that affects the lungs and is caused by Mycobacterium tuberculosis. "Lung sections of patients with pulmonary tuberculosis (n = 13) were immunostained for TCRαβand the macrophage markers CD68 and CD163, respectively." (PMID 22114556, 2011). "In conclusion, endometrial tuberculosis (ETB) exhibit distinct immunological features compared to pulmonary tuberculosis (PTB), particularly in the expression of macrophages CD68, HLA-G, and IL-1Ra." (PMID 40375897, 2025).
renal carcinoma (4 papers, 2018 to 2023). A carcinoma arising from the epithelium of the renal parenchyma or the renal pelvis. "We further confirmed the presence of high number of macrophages in cancer tissues collected from renal carcinoma patients by measurement of CD68 (macrophage marker) and CD206 (M2 macrophage marker)." (PMID 35637970, 2022). "In sarcoid-like lesion in renal cancer, epithelioid cells of the granuloma stained CD68-positive." (PMID 37509363, 2023). "Interestingly, a unique feature in renal cancer was an abundance of CD68+/CD11c+ (2.2–13% of the CD68-mask) and CD68+/CD163+/CD11c+ (3.5–15%) pixels." (PMID 30619287, 2018). "While the density of CD68+ TAMs was similar in primary renal cancer and brain metastases, the CCR2-positive TAMs (proinflammatory type) were more frequently expressed in brain metastases than in primary renal cancer." (PMID 36527157, 2022).
rosacea (4 papers, 2021 to 2023). A chronic erythematous skin disorder that affects the face. "TLR2, KLK5, cathelicidin peptides, and CD68 are all highly expressed in patients with rosacea and rosacea animal models." (PMID 38193038, 2023). "Skin samples of patients with rosacea were subjected to histopathological (hematoxylin and eosin) and immunohistochemical (CD68, Toll-like receptor 2 (TLR2), kallikrein 5, cathelicidin, TNF-α, and IL-1β) evaluation." (PMID 34322115, 2021). "Moreover, EGCG also reduced the expressions of the neutrophil-attracting chemokines (Cxcl15 and Cxcl1), macrophage markers (Cd68 and Itgam), and mast cell-related genes (Tpsab1 and Cma1) in LL-37-induced rosacea-like lesions." (PMID 36937834, 2023). "Moreover, TLR2, KLK5, cathelicidin peptides, and CD68 were highly expressed in both patients with rosacea and rosacea-like animals." (PMID 34322115, 2021). "The CD68+ cells were found to be vastly distributed in granulomatous areas and interfollicular areas in cases of papulopustular rosacea, whereas a perivascular diffuse pattern was mainly observed in cases of erythematotelangiectatic rosacea." (PMID 33545988, 2021). "CD68 immunohistochemical staining showed a large number of brown particles in the skin lesion area, which was significantly enhanced compared to that in the surrounding area of the skin lesion, suggesting a large amount of macrophage infiltration in the rosacea lesion area." (PMID 33545988, 2021). "The results of CD68 and TLR2 immunofluorescence staining showed that in the LL-37+CMC-Na group, rosacea-like inflammatory skin expressed more TLR2 on the surface of aggregated macrophages whereas this was significantly reduced on the surface of macrophages in the LL-37+carvedilol group." (PMID 34322115, 2021).
scleroderma (4 papers, 2011 to 2022). Scleroderma is a rare autoimmune connective tissue disorder characterized by abnormal hardening of the skin and, sometimes, other organs. "The result of immunofluorescence colocalization showed the presence of activated GSDMD in CD68-positive macrophages, suggesting that the pyroptosis of macrophages existed in scleroderma." (PMID 35396386, 2022). "The number of CD68-positive macrophages increased in the BLM-induced scleroderma skin compared with the control, and EchA co-treatment suppressed BLM-induced macrophage infiltration." (PMID 33922418, 2021). "To explore the role of Fpr2 in WKYMVm-induced alleviation of inflammatory responses in scleroderma mice, we next quantified the number of CD68-positive macrophages in Fpr2 knockout mice." (PMID 31552041, 2019). "In this study, we demonstrated that WKYMVm treatment reduced the number of CD68+CD163+ or CD68+Arginase-I+ M2 macrophages in the scleroderma tissues through Fpr2-dependent mechanism." (PMID 31552041, 2019). "The number of CD68-positive macrophages increased in the BLM-induced scleroderma skin compared with that in PBS-treated control specimens; however, this effect was suppressed by WKYMVm treatment." (PMID 31552041, 2019). "Monocytes appear to be able to differentiate into an endothelial precursor population, and a chimeric cell that is CD68 (+), S-100 (+), and CD14 (−) has been implicated in diseases such as scleroderma." (PMID 21483855, 2011). "The number of M1 macrophages, which include CD68+TLR2+ and CD68+NOS2+ cells, were increased in BLM-treated scleroderma skin, and EchA co-treatment reduced the number of M1 macrophages." (PMID 33922418, 2021). "In this study, we showed that BLM-induced scleroderma stimulated infiltration of CD68-positive macrophages into scleroderma skin, and the serum levels of the inflammatory cytokines, TNF-α and INF-γ, were up-regulated in the scleroderma model; however, WKYMVm treatment attenuated these effects." (PMID 31552041, 2019). "Therefore, we quantified the numbers of M2 macrophages, which include CD68+CD163+ or CD68+Arginase-I+ populations, and M1 macrophages including CD68+NOS2+ and CD68+TLR2+ populations in scleroderma skin." (PMID 31552041, 2019). "In contrast to the WKYMVm-induced inhibition of CD68-positive macrophage infiltration in the scleroderma skin of wild type mice, WKYMVm treatment had no significant impact on BLM-induced infiltration of macrophages in Fpr2 KO mice." (PMID 31552041, 2019). "Moreover, WKYMVm treatment did not reduce the numbers of CD68+CD163+ or CD68+Arginase-I+ M2 macrophages in scleroderma skin of Fpr2 KO mice, in contrast to the WKYMVm-induced decrease of M2 macrophage levels in that of wild type mice." (PMID 31552041, 2019). "Moreover, the numbers of M1 macrophages including CD68+NOS2+ and CD68+TLR2+ populations increased in BLM-induced scleroderma skin; however, the BLM-induced increase of M1 macrophage (CD68+NOS2+ and CD68+TLR2+) populations was not significantly affected by WKYMVm treatment." (PMID 31552041, 2019).
tendinopathy (4 papers, 2018 to 2023). "Combined with the effect of PA on CD68+ macrophages in vivo, we proved that PA promoted M2 macrophage polarization and thereby attenuated collagenase-induced tendinopathy." (PMID 36899012, 2023). "The treatment also increased muscle levels of IL-10, and prevented the elevation of CD68+ macrophages in several tissues as well as task-induced tendinopathy, similar to other types of manual therapies, as discussed further below." (PMID 33952219, 2021). "CD68 staining showed few CD68+ cells in the Achilles tendon after DI, suggesting that inflammation did not play a major role in DI induced tendinopathy." (PMID 35166070, 2022). "CD68+ cells were seldom seen in either ITR and control mice, suggesting inflammation did not play a major role in ITR induced tendinopathy." (PMID 35166070, 2022).
Type 1 diabetes (4 papers, 2017 to 2025). "The only exception were type 1 diabetes IDIs, with a lower proportion of CD68+ cells than islets of Aab+ donors (1.8±2.5% vs 2.5±7.5%, respectively)." (PMID 41000615, 2025). "The mean percentage of cells expressing CD68 in the type 1 diabetes group was 8.6±4.7% compared to 3.2±2.7% and 1.5±0.5% in the Aab+ and non-diabetic groups, respectively (p=0.01)." (PMID 41000615, 2025). "In type 1 diabetes, ICIs exhibited a greater proportion of CD68+ cells than their exocrine regions (10.8±10.2% vs 7.9±4.7%) while IDIs had a lower proportion of CD68+ cells (1.8±2.5%)." (PMID 41000615, 2025). "The proportion and density of CD68+ cells were sustained at similar levels to that found in the first ring for the subsequent 7 rings for all groups except around the ICIs of the type 1 diabetes group." (PMID 41000615, 2025). "Concordantly, the density of CD68+ cells was higher in the type 1 diabetes group (856.3±508.2 cells/mm2) than in the Aab+ (312.8±268.4 cells/mm2) or non-diabetic (136.6±56.3 cells/mm2) groups (p=0.01)." (PMID 41000615, 2025). "In subjects with longstanding Type 1 diabetes all the scattered Cathelicidin+ stained cells co-stained with CD68." (PMID 38717484, 2024). "In the donor that died at onset of Type 1 diabetes the scattered Cathelicidin+ cells co-stained with NES or CD68." (PMID 38717484, 2024). "Likewise, comparison of the density of CD68+ cells between the islet region and the first ring found similar results with higher CD68 densities for the type 1 diabetes donors." (PMID 41000615, 2025). "Cell quantification of macrophages throughout the entire tissue section, noted that patients with type 1 diabetes had a statistically significantly increased percentage of total cells expressing CD68 compared to the non-diabetic and Aab+ patients." (PMID 41000615, 2025). "CD68+ cells represented 19.6±14.3%, 9.5±8.1%, 3.9±6.9%, and 1.9±4.5% of the total cells in the peri-islet regions of the type 1 diabetes ICI, type 1 diabetes insulin-deficient islets (IDI), Aab+, and non-diabetic groups, respectively." (PMID 41000615, 2025). "Cutaneous wound closure, CD68- and arginase-1 (Arg-1)-expressing macrophages, and cytokine mRNA expression were examined in non-diabetic and streptozotocin-induced type 1 diabetic mice at different time points after injury." (PMID 28542434, 2017). "In streptozotocin (STZ) induced type 1 diabetes mellitus (T1DM) mouse model, CD45+ and CD68+ macrophages are the most abundant leukocytes accumulating in glomerular and interstitial tissues of kidneys." (PMID 36405700, 2022). "Within the first ring, the proportion of CD68+ cells were 13.6±5.1%, 7.5±4.0%, 2.6±2.4%, and 1.3±0.4% compared with 6.2±4.2%, 1.6±1.5%, 0.4±0.5%, and 0.3±0.1% of the islet region for the type 1 diabetes ICI, type 1 diabetes IDI, Aab+, and non-diabetic groups, respectively." (PMID 41000615, 2025).
viral myocarditis (4 papers, 2022 to 2025). Myocarditis that is caused by an infection with a viral agent. "Immunohistochemical analysis of cardiac tissue revealed inflammatory infiltrates consisting of both T cells (CD3) and macrophages (CD68) in patients with immune-mediated and viral myocarditis." (PMID 34910083, 2022). "Indeed, the Kindermann study group also reports examples of acute phase viral myocarditis with myocyte necrosis and mononuclear infiltrate that includes CD3+ T lymphocytes and B lymphocytes, and examples of chronic viral myocarditis with CD68+ macrophage infiltrate and areas of fibrosis." (PMID 38611673, 2024). "We next stained for macrophages (CD68) and T cells (CD3) as these cells are commonly involved in the pathogenesis of viral myocarditis and contribute to inflammatory infiltrates." (PMID 40304490, 2025).